WNT4 (Wnt family member 4)
Diseases named in the same sentence as WNT4 in open-access papers (continued):
Sharing a sentence is not in itself a finding about the gene and the disease.
diabetes (7 papers, 2021 to 2024). "Significantly higher Wnt4 expression was observed only in the proximal convoluted tubules in the DM group two weeks after diabetes induction." (PMID 36294921, 2022). "Wnt4 is the most abundantly expressed Wnt protein in β‐cells, whereas its role in diabetes is also contradicting because it functions as a biphasic initiator for canonical and non‐canonical Wnt pathways." (PMID 34042263, 2021). "Thus, the increase of Wnt4 in individuals with diabetes can indirectly affect the osteogenesis process by affecting insulin synthesis." (PMID 37106471, 2023). "However, Wnt4 expression in islet cells of individuals with diabetes is increased, leading to enhancement of the JNK pathway in Wnt/PCP signaling, which impairs β cell proliferation and insulin secretion." (PMID 37106471, 2023). "Compared with the conflicting role of canonical Wnt pathway, non‐canonical Wnt pathways are consistently overactivated in diabetes and related complications, and the expression of related Wnts, including Wnt4, Wnt5a, Wnt5b and Wnt11, is increased in diseased tissues in diabetic environment." (PMID 34042263, 2021). "Next, the role of genes such as Wnt4 must be inferred with caution, owing to their heterogeneity and biphasic involvement in both canonical and non-canonical pathways, and mainly due to a lack of deeper understanding of their precise role in diabetes and related disorders." (PMID 38891081, 2024). "The re-expressed WNT4 could increase rat glomerular mesangial cell growth in vitro through suppressing GSK-3β and improving β-catenin activity, while knocking down the WNT4 expression during experimental diabetes significantly promoted mesangial cell apoptosis." (PMID 34642299, 2021).
gastric cancer (7 papers, 2016 to 2024). A primary or metastatic malignant neoplasm involving the stomach. "The main active metabolite, indole-3-methanol, 3,3′-diindolylmethane (DIM), prevents and treats cancers by inhibiting cell proliferation and inducing apoptosis; however, low-dose DIM induced WNT4 secretion and promoted gastric cancer progression." (PMID 38952556, 2024). "Previously, we found that low levels of DIM activated Wnt4 autocrine signaling to enhance the progression of gastric cancer cells." (PMID 33842314, 2021). "Taken together, these results suggest that low level of DIM promotes gastric cancer progression via Wnt4 autocrine." (PMID 26918831, 2016). "We found that the expression of Wnt4 was obviously increased in gastric cancer cells treated with low level of DIM." (PMID 26918831, 2016). "We found that the expression of Wnt4 protein was increased in the gastric cancer cells treated with low level of DIM by using western blot and immunofluorescent staining." (PMID 26918831, 2016). "In summary, we demonstrate in this study that low level of DIM promotes gastric cancer progression through Wnt4 autocrine and the activation of β-catenin pathway." (PMID 26918831, 2016). "Low level of DIM promoted gastric cancer progression by inducing the PORCN-dependent secretion of Wnt4 and the activation of β-catenin signaling." (PMID 26918831, 2016). "However, it has also been shown that anti-cancer dosage of DIM can activate autocrine Wnt4 signaling to promote gastric cancer." (PMID 33842314, 2021). "Recent study revealed that MSCs can secret exosomes delivered Wnt4, and exosomal Wnt4 could enhance gastric cancer cell stemness and tumorigenesis." (PMID 28145881, 2017). "Taken together, our findings indicate that low level of DIM activates autocrine Wnt4 signaling to enhance the progression of gastric cancer, which may suggest an adverse aspect of DIM in cancer therapy." (PMID 26918831, 2016). "Wnt4 knockdown reversed the effects of low level of DIM on gastric cancer cells." (PMID 26918831, 2016). "The promoting effects of low level of DIM on gastric cancer cells are dependent on Wnt4 secretion." (PMID 26918831, 2016). "We found that low level of DIM (1 μM and 10 μM) could obviously promote gastric cancer cell proliferation, migration, and stemness through the activation of autocrine Wnt4/β-catenin signaling." (PMID 26918831, 2016). "Moreover, as demonstrated in this study, the activation of Wnt4 signaling is required by low level of DIM in promoting gastric cancer progression, probably simultaneous targeting Wnt4 may help improve therapeutic efficacy." (PMID 26918831, 2016). "The results of in vivo studies showed that gastric cancer cells treated with low level of DIM (1 μM) grew faster and expressed higher level of Wnt4 than control cells." (PMID 26918831, 2016).
invasive lobular carcinoma (7 papers, 2016 to 2024). "The study also agrees with the observation that the expression of the WNT4 gene, along with the action of WNT4 glycoprotein, is directly regulated by estrogen in invasive lobular breast carcinoma cell lines." (PMID 37835474, 2023). "Moreover, in the case of invasive lobular carcinoma, it has been reported that a member of the Wnt protein family, WNT4, is transcriptionally induced by estrogen receptors and drives non-canonical Wnt signaling in lobular cancer cells." (PMID 33808143, 2021). "In models of invasive lobular carcinoma of the breast (ILC), ER-driven WNT4 signaling is critical for cell proliferation and survival, but downstream signaling mediated by ER:WNT4 is unknown." (PMID 33053661, 2020).
melanoma (7 papers, 2008 to 2024). A malignant, usually aggressive tumor composed of atypical, neoplastic melanocytes. "Among them, WNT3 and WNT4 were implied as melanoma tumor suppressors; WNT7A and WNT10A displayed contribution to the female reproductive system adenocarcinomas." (PMID 35850748, 2022). "For instance, WNT3 and WNT4 are implied as a tumor suppressor of melanoma." (PMID 35850748, 2022). "The WNT4 protein can be considered a favorable prognostic marker in pancreatic cancer and an unfavorable prognostic marker in melanoma, but not in the pathologically altered uterus or other reproductive organs." (PMID 37835474, 2023). "WNT11, WNT9A and WNT4 were tumor negative WNTs, which were abundant in normal tissues, while declining in many tumors including melanoma, sarcoma, breast adenocarcinoma and colorectal adenocarcinoma." (PMID 35850748, 2022). "This leaves WNT4, CHP2, PPP2R2C and COL11A1 which have not been previously reported to be associated with melanoma." (PMID 23638386, 2013). "However, six signature genes (i.e., IL8, SHC4, COL11A1, CHP2, PPP2R2C and WNT4) were not reported previously by microarray-based melanoma studies, although two (i.e. IL8 and SHC4) have been identified in independent wet-lab studies." (PMID 23638386, 2013).
Müllerian aplasia (6 papers, 2014 to 2024). "While the exact cause of MRKH remains unknown, mutations in the WNT4 gene and elevated androgen levels have been associated with Müllerian aplasia." (PMID 39185296, 2024). "Furthermore, mutations in the WNT4 gene also cause WNT4 Müllerian aplasia and ovarian dysfunction." (PMID 25270402, 2014).
SERKAL syndrome (6 papers, 2014 to 2024). SERKAL (SEx Reversion, Kidneys, Adrenal and Lung dysgenesis) syndrome is characterized by female to male sex reversal and developmental anomalies of the kidneys, adrenal glands and lungs. "WNT4 and its frizzled cell surface receptors have a role in the induction of female sex differentiation, and when both alleles of WNT4 are inactive, SERKAL syndrome (sex reversal, kidneys, adrenal, and lung dysgenesis; MIM# 611812) occurs." (PMID 38812815, 2024). "An increase in WNT4 copies in humans was shown to result in a male-to-female sex reversal in 46,XY patients, while WNT4 inactivation or mutation resulted in sex reversion–kidneys, adrenal, and lung dysgenesis (SERKAL) syndrome or virilization." (PMID 35886859, 2022). "SeRKAL syndrome (female sex reversal and dysgenesis of kidneys, adrenals, and lungs) has been reported in a single family with homozygous disruptive mutations in WNT4, a signaling molecule implicated in adrenal development." (PMID 33381483, 2020). "Even though previous reports have shown adrenal dysgenesis in patients with inactivating mutations of WNT4 in the context of SERKAL syndrome, profound developmental defects resulted in embryonic lethality, precluding evaluation of adrenal differentiation and endocrine activity." (PMID 36538378, 2023).
colon carcinoma (5 papers, 2007 to 2024). "Pearson correlation analysis of transcriptome data from 14 patients with colon cancer indicated strong positive correlations between WNT4 and STAT3, and between STAT3 and IGF2." (PMID 39373342, 2024). "Additionally, multiplex immunofluorescence analyses of pathological sections from 25 patients with colon cancer confirmed co‐expression of WNT4, STAT3, and IGF2." (PMID 39373342, 2024). "Traditionally, unraveling the mechanisms involving WNT4 and IGF2 in colon cancer would require extensive literature reviews or costly high‐throughput screening technologies." (PMID 39373342, 2024). "A significant highlight of this work is our innovative use of GENET to discover and validate a new pathway in colon cancer, specifically, the promotion of IGF2 by WNT4 through the activation of STAT3." (PMID 39373342, 2024). "In the YUMC-C1 and YUMC-C2 drug-resistant and metastatic colon cancer cells, respectively, metastatic genes (CDH2, KRAS, CDC42, MCPH1, SRGAP) and markers of stemness (BRACA1 and 2, CD44, KRT5, WNT4, CD29, SAL4) were markedly enhanced." (PMID 33050525, 2020). "Some of these inhibitors are Wnt target genes, for example, DKK4, an inhibitor that is expressed in human colon cancer, and SFRP2, a secreted Wnt inhibitor induced by Wnt4 in the developing kidney." (PMID 28183841, 2017). "Secondly, while we have identified and validated a potential mechanism involving WNT4, STAT3, and IGF2 in colon cancer using sequencing data and immunofluorescence techniques, additional technologies such as WB and PCR are required to verify their regulatory relationships." (PMID 39373342, 2024).
laryngeal carcinoma (5 papers, 2020 to 2023). Carcinoma that arises from the laryngeal epithelium. "Using both in vivo and in vitro models, we demonstrated that PRMT5 can facilitate EMT and lymph-node metastasis of laryngeal carcinoma cells via modulating the Wnt4/β-catenin pathway." (PMID 33060569, 2020). "The PRMT5/WNT4 axis intensifies proliferation and lymph node metastasis of laryngeal carcinoma." (PMID 34476262, 2021). "Mechanistic explorations showed that PRMT5 could regulate tumorigenesis and metastasis of laryngeal carcinoma by activating the Wnt4/β-catenin signaling pathway." (PMID 33060569, 2020). "We further investigated whether PRMT5-induced proliferation of laryngeal carcinoma cells and metastasis was Wnt4-dependent." (PMID 33060569, 2020). "The oncogenic role of protein arginine methyltransferase 5 (PRMT5) could activate the WNT4/β-catenin signaling pathway to induce laryngeal carcinoma cell proliferation, migration, and invasion in vitro, as well as lymph node metastasis in vivo, while silencing WNT4 could reverse the effect of PRMT5." (PMID 34642299, 2021). "In this study, we demonstrated that PRMT5 is a coactivator to enhance the formation of β-catenin in the nucleus of laryngeal carcinoma cells, this signaling might be at least partly mediated by Wnt4, and the PRMT5/Wnt4 axis could be a new mechanism in laryngeal carcinoma development." (PMID 33060569, 2020). "In laryngeal carcinoma, PRMT5 regulates WNT4 expression, and PRMT5–WNT4 activates β-catenin to induce cadherin 2 (CDH2: also known as N-cadherin) and SNAIL expression, which is involved in EMT and promotes cell migration and lymph-node metastasis." (PMID 36980950, 2023). "We first examined the protein levels of the key molecular markers, including cyclin D1, Wnt4, MYC, Wnt7A, and Wnt9A, of the Wnt/β-catenin signaling pathway in laryngeal carcinoma cells." (PMID 33060569, 2020). "Immunofluorescent staining results showed that the subcellular localization of β-catenin was mainly in the nucleus after overexpression of Wnt4 in PRMT5-depleted cells, which indicated that the β-catenin accumulation in the nucleus is necessary for PRMT5–Wnt4-induced laryngeal carcinoma metastasis." (PMID 33060569, 2020). "Collectively, these results suggested that PRMT5 regulated proliferation via the Wnt4/β-catenin axis in laryngeal carcinoma, and the PRMT5/Wnt4 axis may serve as a potential therapeutic target for laryngeal carcinoma." (PMID 33060569, 2020).
osteoporosis (5 papers, 2016 to 2025). A condition of reduced bone mass, with decreased cortical thickness and a decrease in the number and size of the trabeculae of cancellous bone (but normal chemical composition), resulting in increased fracture incidence. "An in vivo study showed that WNT4 attenuated bone loss in osteoporosis and skeletal aging mouse models by promoting bone formation and inhibiting bone resorption." (PMID 34642299, 2021). "The scaffold's ability to upregulate Wnt4, Wnt5a, and Wnt10b expression enhances osteogenic differentiation, reversing the Wnt inhibition characteristic of osteoporosis." (PMID 41542097, 2025). "The gene expression profile demonstrated that WNT4, WNT3a, and WNT5a were significantly downregulated in the bone tissue of patients with primary osteoporosis." (PMID 34642299, 2021). "Another in vivo study showed that MSCs genetically engineered to express WNT4 could enhance osteogenesis and improve the repair of craniofacial defects in two different models of craniofacial bone injury, suggesting that WNT4 protein may prove to be a potential target for osteoporosis treatment." (PMID 34642299, 2021). "A recent study reported that curculigoside, the active anti-osteoporosis compound extracted from Curculigo orchioides Gaertn, could targetedly activate ERK1 and then regulate the WNT4 expression in MC3T3-E1 cells (data under submission)." (PMID 34642299, 2021).
pituitary adenomas (5 papers, 2013 to 2025). "Wnt4 had been reported to activate canonical Wnt signaling pathways in human pituitary adenomas, and is associated with tumor invasion in cutaneous cells." (PMID 33060569, 2020). "The overexpression of WNT4 has been observed in various subtypes of pituitary adenoma, but it displays an inverse correlation with tumor invasion." (PMID 31796052, 2019). "Additional genes—PHYHD1, LTBR, MYBPHL, C22orf42, PRR5, ANKDD1A, RAB13, CAMKV, KIFC3, WNT4, and STAT6—were implicated in the invasive behavior of non-functioning pituitary adenomas (NFPAs)." (PMID 39859246, 2025). "There is increasing evidence that WNT4 signals through a non-canonical pathway in many cell types, such as β-cells, human anaplastic thyroid carcinomas, murine hematopoietic progenitor cells, and human pituitary adenomas." (PMID 24274766, 2013).
renal agenesis (5 papers, 2010 to 2025). Renal agenesis (RA) is a form of renal tract malformation characterized by the complete absence of development of one or both kidneys (unilateral RA or bilateral RA respectively), accompanied by absent ureter(s). "A missense variant of WNT4 has also been reported with another uterovaginal anomaly with renal agenesis (Herlyn-Werner-Wunderlich syndrome)." (PMID 38699388, 2024). "A heterozygous mutation in WNT4, encoding a signaling molecule that is thought to repress tissue-specific androgen production in female embryos, has been reported in a female with Müllerian abnormalities associated with unilateral renal agenesis." (PMID 20811621, 2010). "We were unable to investigate the effect of ectopic IHCs on hearing because Wnt4 mutants die within 24 h after birth due to renal agenesis, a congenital disability where one or both kidneys fail to develop." (PMID 40558515, 2025).
thymoma (5 papers, 2021 to 2025). A neoplasm arising from the epithelial cells of the thymus. "Thymic carcinomas and B3 thymomas exhibit increased expression of WNT4 compared to the normal thymus." (PMID 38201593, 2023). "In line with this peculiarity of TETs, induced WNT4 expression in thymoma-derived pTECs was positively correlated with the expression of FOXN1." (PMID 35965500, 2022). "PTECs cultured in 3D models prevented the time-dependent decline of WNT4 mRNA expression in thymoma-derived pTECs, suggesting the operation of an autocrine loop in the 3D settings." (PMID 35965500, 2022). "This is a key new finding that WNT4/FZD6 appears to be particularly relevant for developing the most aggressive TETs (B3 thymomas and TCs) since they showed the most abnormally increased mRNA levels of WNT4/FZD6." (PMID 35965500, 2022). "Another study showed that the activation of JNK pathway by WNT4 overexpression was mediated in the development of thymoma." (PMID 34642299, 2021). "Our results suggest that WNT4 signaling drives thymoma oncogenesis and that acute blocking of WNT4 signaling—under a therapeutic perspective—might induce resistance through AKT/NF-κB activation." (PMID 35965500, 2022). "In biopsy, WHO classified B3 thymomas and TCs showed increased WNT4 expression compared with NTs." (PMID 35965500, 2022). "The conclusion of WNT4 expression and secretion in the most aggressive TETs (B3 thymomas and TCs) is strongly underpinned by our in vitro experiments, since the rich conditioned medium could postpone senescence, maintain proliferation, and extend the survival of neoplastic pTECs grown in vitro." (PMID 35965500, 2022). "The downregulation of WNT4 by shRNA induced cell death in primary cultures of B3 thymomas and resulted in decreased RAC1 expression without JNK phosphorylation." (PMID 38201593, 2023). "In addition to WNT4, the WNT2 gene was strongly expressed in B2 thymomas compared with B3 thymomas and TCs." (PMID 35965500, 2022). "Down-regulation of WNT4 by shRNA induced cell death in pTECs derived from B3 thymomas and led to decreased RAC1, but not JNK protein phosphorylation." (PMID 35965500, 2022). "WNT4 secretion was evaluated in whole tissues of normal thymuses (six childhood and 10 aged NT) and thymic tumors (10 AB, 10B2 and 10B3 and 8TC) and was significantly higher in B3 thymomas and TCs compared with childhood and aged non-neoplastic thymuses." (PMID 35965500, 2022). "Considering that the most aggressive TETs, B3 thymomas, and TCs showed combined increased expression of WNT4, its non-canonical frizzled receptor 6 (FZD6), and downstream non-canonical WNT/JNK activity, TETs appear as promising candidates for trials testing novel inhibitors of WNT and JNK." (PMID 35965500, 2022). "Resent research investigates the role of WNT4 signaling in TETs, finding that WNT4 and its receptor FZD6 are overexpressed in aggressive B3 thymoma and thymic carcinoma, unlike their age-related decline in normal thymus." (PMID 40805209, 2025). "Expression and function of WNT4 and FZD6 were analyzed using qRT–PCR, Western blot, ELISA, in biopsies of non-neoplastic thymi (NT), thymoma and thymic carcinomas." (PMID 35965500, 2022).